CHCHD2 (coiled-coil-helix-coiled-coil-helix domain containing 2)
Description:
Transcription factor. Binds to the oxygen responsive element of COX4I2 and activates its transcription under hypoxia conditions (4% oxygen), as well as normoxia conditions (20% oxygen).
Synonyms: NS2TP; C7orf17; MIX17B; MNRR1; PARK22
Tractability: PROTAC: ubiquitination databases record sites on it; its protein half-life has been measured.
Gene: Protein-coding gene on chromosome 7 (56,094,567 to 56,106,505, reverse strand). Ensembl gene ENSG00000106153.
Subcellular location: Nucleus; Mitochondrion; Mitochondrion intermembrane space
Subcellular location (Human Protein Atlas): Mitochondria
Pathways (Reactome):
Metabolism of proteins: Mitochondrial protein degradation
Protein localization: Mitochondrial protein import
Gene Ontology:
Molecular function: DNA-binding transcription factor binding; protein binding; sequence-specific DNA binding
Biological process: cellular response to oxidative stress; positive regulation of mitochondrial ATP synthesis coupled electron transport; positive regulation of transcription by RNA polymerase II; regulation of cellular response to hypoxia; regulation of generation of precursor metabolites and energy; mitochondrion organization
Cellular component: mitochondrial intermembrane space; mitochondrion; nucleus
Genetic constraint (gnomAD): Loss-of-function variants: 17 observed, 16 expected, observed/expected ratio (o/e) 1.06, 90% interval 0.73 to 1.59. The upper end of that interval is the gene's LOEUF score, 1.59, which puts it in group 6 of 6, group 1 being the genes least tolerant of losing a copy. Missense variants: 175 observed, 196.5 expected, observed/expected ratio (o/e) 0.89, 90% interval 0.79 to 1.01. Synonymous variants: 63 observed, 71.31 expected, observed/expected ratio (o/e) 0.88, 90% interval 0.72 to 1.09.
Homologues: Orthologues: chimpanzee CHCHD2 (100% identical), macaque CHCHD2 (98% identical), pig CHCHD2 (92% identical), dog CHCHD2 (90% identical), rat Chchd2 (87% identical), mouse Chchd2 (87% identical), rat Chchd2l3 (86% identical), guinea pig CHCHD2 (82% identical), tropical clawed frog chchd2 (79% identical), zebrafish chchd2 (70% identical), Drosophila melanogaster Chchd2 (52% identical). Paralogues in human: CHCHD10 (54% identical).
Diseases named in the same sentence as CHCHD2 in open-access papers:
CHCHD2 is named in the same sentence as 63 diseases in open-access papers, as found by Europe PMC text mining. Sharing a sentence is not in itself a finding about the gene and the disease. The quoted sentences say what the papers report.
Parkinson disease (43 papers, 2017 to 2026). A progressive degenerative disorder of the central nervous system characterized by loss of dopamine producing neurons in the substantia nigra and the presence of Lewy bodies in the substantia nigra and locus coeruleus. "In 2015, CHCHD2 was identified for the first time to be significantly associated with inherited Parkinson’s disease." (PMID 40963812, 2025). "Mutations in genes encoding mitochondrion-associated proteins, including PINK1, parkin, DJ-1, and CHCHD2, have been shown to cause progressive and human-like Parkinsonism, demonstrating that mitochondrial dysfunction is sufficient to induce neuronal injury." (PMID 39964974, 2025). "For example, CHCHD2 is a mitochondrial protein definitively associated with Parkinson’s disease and an interaction partner of the ALS protein CHCHD1044." (PMID 38697975, 2024). "Genetic analysis and experimental evidence indicate a strong correlation between CHCHD2 gene mutations and Parkinson’s disease (PD) and Lewy body disease (LBD)." (PMID 38341417, 2024). "Mutations in CHCHD2 have been linked to Parkinson’s disease, however, their exact pathophysiologic roles are unclear." (PMID 38395904, 2024). "CHCHD2 gene expression has also been found to be significantly reduced in post-mortem brains of individuals with Parkinson’s disease, and mutations within the protein have been reported to promote alpha-synuclein aggregation." (PMID 38697975, 2024). "Parkinson 22 is a form of Parkinson’s Disease caused by mutations on theCHCHD2 gene; however, few CHCHD2 variants are characterized." (PMID 38188421, 2023). "Parkinson 22 is a form of Parkinson’s disease caused by variations in the coiled-coil-helix-coiled-coil-helix domain containing 2 (CHCHD2) protein." (PMID 38188421, 2023). "CHCHD2 gene locus mutations are closely related to Parkinson’s disease and other neurodegenerative diseases." (PMID 36477358, 2022). "In the age-associated neurodegenerative disorder known as Parkinson’s disease, pathogenic variants of the mitochondrial membrane factor CHCHD2 were shown to stimulate UPRmt via CHCHD2 nuclear relocalization and via CHCHD10 oligomerization." (PMID 34943861, 2021). "Rare mutations in the mitochondrial protein coiled-coil-helix-coiled-coil-helix domain containing 2 (CHCHD2) are associated with Parkinson’s disease (PD) and other Lewy body disorders." (PMID 33967741, 2021). "Changes in differential gene expression of the lipid metabolism network identified the Parkinson’s risk gene CHCHD2 (PARK 22) as significantly downregulated in the neurons carrying the p.A30P SNCA mutation compared to the gene-corrected isogenic control." (PMID 34754035, 2021). "CHCHD2 mutations are already associated with several neurodegenerative diseases, including frontotemporal dementia and Parkinson’s disease, while CHCHD10 mutations have also been found to cause ALS." (PMID 34660586, 2021). "Recent studies suggest that CHCHD2 regulates the functions of cytochrome c and that the loss of this regulation is associated with Parkinson’s disease." (PMID 33921034, 2021). "Variants of CHCHD2 have been linked to Parkinson's disease and CHCHD2 is reportedly found to possess role of transcription factor." (PMID 33537311, 2020). "CHCHD2 recently gained attention as mutations in this gene have been associated with neurodegenerative diseases, including Parkinson's Diseases." (PMID 32467259, 2020). "Very recently, we identified a novel causative gene for Parkinson’s disease (CHCHD2) localized in the mitochondrial intermembrane space." (PMID 28779141, 2017). "For example, LMX1A and CHCHD2 have been previously associated with Parkinson’s disease." (PMID 38697975, 2024). "In a limited case study, several exonic variants that may affect CHCHD2 protein levels or subcellular localization showed an association with Parkinson’s disease." (PMID 37190500, 2023). "Mutations of CHCHD2 are mainly linked to Parkinson’s disease." (PMID 35173147, 2022).
Parkinson disease (continued). "Furthermore, numerous genes have recently been implicated in Parkinson’s disease, such as CHCHD2, LRP10, TMEM230, UQCRC1, and VPS13C." (PMID 35328025, 2022). "Two proteins with typical CX9C cysteine motifs called coiled-coil-helix-coiled-coil-helix domain containing protein 2 (CHCHD2) and 10 are linked to several neurodegenerative diseases such as Parkinson's disease (PD), AS, ALS and frontotemporal lobe dementia (FTD)." (PMID 33715390, 2021). "Mutations in CHCHD2 are associated with Parkinson's disease." (PMID 28589937, 2017). "Mutations in CHCHD2 have been identified in some Parkinson's disease (PD) cases." (PMID 28589937, 2017). "Research indicates that mutations in the CHCHD2 gene may contribute to the pathogenic mechanisms underlying neurodegenerative diseases such as Parkinson’s disease, frontotemporal dementia, and Alzheimer’s disease, and are also associated with apoptosis and cancer." (PMID 40963812, 2025). "In Drosophila, the loss of CHCHD2 can lead to abnormalities in the mitochondrial matrix structure and impaired mitochondrial respiration, which exacerbates the sensitivity to oxidative stress, loss of dopaminergic neurons, and motor dysfunction associated with Parkinson’s disease." (PMID 37190500, 2023). "Additionally, variants in the related protein CHCHD2 have been linked to Parkinson’s disease." (PMID 38020590, 2023). "CHCHD2 and CHCD10, genes associated with Parkinson's disease (PD) and amyotrophic lateral sclerosis-frontotemporal dementia (ALS-FTD), respectively, are localized within the mitochondrial intermembrane space." (PMID 39131911, 2024). "CHCHD2 and CHCHD10, linked to Parkinson's disease and amyotrophic lateral sclerosis-frontotemporal dementia (ALS), respectively, are mitochondrial intermembrane proteins that form a heterodimer." (PMID 39131911, 2024). "In the literature, there is a reference of its parental gene CHCHD2 to the pathogenesis of Parkinson’s disease." (PMID 33921034, 2021). "In recent years, mutations of CHCHD2 and CHCHD10 are widely linked to a series of neurodegenerative diseases, including Parkinson's disease, amyotrophic lateral sclerosis and frontotemporal lobe dementia 12-14." (PMID 31839816, 2019). "Remarkably, the Parkinson disease (PD)-related gene CHCHD2 is also significantly downregulated in all mutant lines, while GAK is upregulated." (PMID 30057263, 2018). "In human cells, MIA substrates have been linked to neurodegenerative diseases such as CHCHD10 (coiled-coil-helix-coiled-coil-helix domain containing 10) in amyotrophic lateral sclerosis and CHCHD2 (coiled-coil-helix-coiled-coil-helix domain containing 2) in Parkinson’s Disease." (PMID 38256258, 2024). "In addition, genetic studies have revealed that many causal genes of monogenic Parkinson’s disease, such as Parkin (PARK2), PINKl (PARK6), DJ-1 (PARK7), Omi/HtrA2 (PARK13), and CHCHD2 (PARK22), are associated with mitochondrial functions and quality control." (PMID 32937849, 2020). "Drosophila models expressing human α-synuclein and human CHCHD2 T61I in a Drosophila ortholog of CHCHD2 and CHCHD10, CG5010 (also known as C2C10H)−/− background reproduced parkinsonism-like phenotypes such as motor disabilities, shortened life span, and α-synuclein aggregation in the brain." (PMID 36158221, 2022). "Newly reported genes for dominant Parkinson’s disease are DNAJC13, CHCHD2, andTMEM230." (PMID 28733970, 2017). "Mutations in CHCHD2 and CHCHD10 contribute to multiple types of neurodegenerative disorders including amyotrophic lateral sclerosis, Parkinson's disease, and frontotemporal dementia, but have not been observed to be lost in aging." (PMID 41496579, 2026). "This review reveals protective effects and mechanisms of CHCHD2 and CHCHD10 in neurodegenerative diseases characterized by cognitive and motor deficits, such as frontotemporal dementia (FTD), Lewy body dementia (LBD), Parkinson’s disease (PD) and amyotrophic lateral sclerosis (ALS)." (PMID 36061599, 2022).
Parkinson disease (continued). "At least 19 genetic loci for Parkinsonism have been identified to date, ten of which are autosomal dominant genes: SNCA (PARK1/PARK4), PARK3, UCHL1 (PARK5), LRRK2 (PARK8), GIGYF2 (PARK11), HTRA2 (PARK13), VPS35 (PARK17), EIF4G1 (PARK18), TMEM230 (PARK21), and CHCHD2 (PARK22)." (PMID 34356877, 2021).
amyotrophic lateral sclerosis (13 papers, 2019 to 2026). Amyotrophic lateral sclerosis (ALS) is a neurodegenerative disease characterized by progressive muscular paralysis reflecting degeneration of motor neurons in the primary motor cortex, corticospinal tracts, brainstem and spinal cord. "Recently, mutations of the genes for mitochondrial twin CX9C proteins, CHCHD2 and CHCHD10, were identified as being linked to the pathogenesis of Parkinson’s diseases (PD), amyotrophic lateral sclerosis (ALS) and frontotemporal lobe dementia (FTD)." (PMID 30791515, 2019). "Second, substrates of the MIA pathway are linked also to primary mitochondrial diseases (such as several mitochondriopathies related to COX deficiencies) and to more common neurodegenerative diseases (such as for example CHCHD2 and CHCHD10, which are linked to amyotrophic lateral sclerosis)." (PMID 33921425, 2021). "Mutations of coiled-coil-helix-coiled-coil-helix domain containing 2 (CHCHD2) and 10 (CHCHD10) have been found to be linked to Parkinson’s disease (PD), amyotrophic lateral sclerosis (ALS), and/or frontotemporal lobe dementia (FTD)." (PMID 30791515, 2019).
frontotemporal dementia (10 papers, 2019 to 2026). Frontotemporal dementia (FTD) comprises a group of neurodegenerative disorders, characterized by progressive changes in behavior, executive dysfunction and language impairment, as a result of degeneration of the medial prefrontal and frontoinsular cortices. "In line with CHCHD2, CHCHD10 has been verified to be involved in multiple neurological alterations including Parkinson’s disease (PD), frontotemporal dementia (FTD), as well as Alzheimer's disease (AD)." (PMID 37438854, 2023).
hepatocellular carcinoma (9 papers, 2015 to 2025). A malignant tumor that arises from hepatocytes. "We and others have found that increased CHCHD2 expression is closely related to hepatocellular carcinoma." (PMID 36477358, 2022). "CHCHD2 indicates a poor prognosis and is overexpressed in hepatocellular carcinoma, breast tumor, non-small cell lung carcinoma, and renal cell carcinoma." (PMID 35449571, 2022). "Consistently, we previously reported that CHCHD2 is highly expressed in hepatocellular carcinoma; however, to date, the role of CHCHD2 in NAFLD remains unknown." (PMID 36477358, 2022). "Our previous study found that CHCHD2 is highly expressed in hepatocellular carcinoma specimens." (PMID 36477358, 2022). "CHCHD2 was not only recorded in hepatocellular carcinoma (HCC) cells but also tissues whereCHCHD2 protein level was remarkably relatable with poor differentiation, lymph node metastasis, local tissue invasion, angiogenesis, and poor prognosis in patients." (PMID 33537311, 2020). "More importantly, potential target genes of CHCHD2 are involved in NAFLD and hepatocellular carcinoma." (PMID 36477358, 2022). "The top 15 enriched Kyoto Encyclopedia of Genes and Genomes (KEGG) pathways (based on the P value) showed that CHCHD2 target genes were involved in 2 liver diseases: NAFLD and hepatocellular carcinoma." (PMID 36477358, 2022). "This study aimed to investigate the role of CHCHD2 in hepatocellular carcinoma (HCC)." (PMID 31839816, 2019).
breast carcinoma (8 papers, 2014 to 2025). "In patients with breast cancer, CHCHD2 was positively correlated with matrix metalloproteinase‐2, and high CHCHD2 expression was related to distant metastasis and poor prognosis." (PMID 40434251, 2025). "The role of CHCHD2 was clearly established in stimulating proliferative and migratory potentials in Docetaxel-resistant breast cancer cells by upregulating MMP2." (PMID 33537311, 2020). "CHCHD2 levels are correlated with increased metastasis and poor prognosis in breast cancer patients." (PMID 33537311, 2020). "Analysis of mRNA microarray expression data obtained from the Oncomine database shows that CHCHD2 is overexpressed in many types of cancers, including breast cancer, glioblastoma, leukemia, lung adenocarcinoma and lymphoma 15-19." (PMID 31839816, 2019). "CHCHD2 was attendant even in invasive ductal carcinoma where the expression of CHCHD2 was recorded twice in malignant tissue compared to benign tissue and about 18 times higher in breast cancer cell lines compared to control cells thereby suggesting its association with invasive metastasis." (PMID 33537311, 2020). "Furthermore, the role of CHCHD2 in apoptosis prevention has been confirmed in adrenal tumors, non-small cell lung cancer, glioblastoma, and breast cancer, although the mechanisms of action vary among these contexts." (PMID 40963812, 2025).
dementia with Lewy bodies (4 papers, 2019 to 2024). "Heterozygous rare variants within the predicted mitochondrial targeting sequence of CHCHD2 are linked to PD and Lewy body disease." (PMID 39131911, 2024). "Recent findings demonstrate that CHCHD2 mutations are associated with late-onset autosomal dominant PD, as well as sporadic PD and dementia with Lewy bodies (DLB)." (PMID 30791515, 2019).
non-small cell lung carcinoma (4 papers, 2021 to 2023). A group of at least three distinct histological types of lung cancer, including non-small cell squamous cell carcinoma, adenocarcinoma, and large cell carcinoma. "A previous study found that over-expression of CHCHD2 could promote the expression of HIF-1α to adapt the hypoxia microenvironment in non-small cell lung cancer." (PMID 36627705, 2023). "Studies have shown that in non-small cell lung cancer (NSCLC), CHCHD2 and HIF-1α co-localise in both the cytoplasm and the nucleus, with CHCHD2 overexpression significantly promoting that of HIF-1α." (PMID 34616772, 2021). "Interestingly, CHCHD2 is co-amplified with EGFR in non-small cell lung carcinoma (NSCLC), and knockdown of CHCHD2 in NSCLC not only reduces cell migration but also cell proliferation and mitochondrial respiration." (PMID 33967741, 2021).
liver cancer (3 papers, 2015 to 2019). An epithelial or non-epithelial malignant neoplasm that arises from the liver. "The function of the novel cell migration-promoting factor, coiled-coil-helix-coiled-coil-helix domain containing 2 (CHCHD2) in liver cancer remains to be elucidated." (PMID 25625293, 2015). "The present study therefore aimed to investigate CHCHD2 expression in liver cancer." (PMID 25625293, 2015).
lung carcinoma (3 papers, 2019 to 2024). "In immunohistochemistry experiments, the expression levels of multiple genes, including CHCHD2, CEACAM5, GAPDH, and CD24, were significantly upregulated in lung cancer tissues compared to normal tissues." (PMID 38872167, 2024). "Thus, we suspect that if the expression of CHCHD2 accompanies the HIF-1α expression participated in the regulation signaling pathways, so that lung cancer cells could adapt to hypoxic environment and play a role in angiogenesis, invasion, metastasis and metabolism of lung cancer." (PMID 32054470, 2020).
lymph node metastasis (3 papers, 2019 to 2025). "In addition, we analyzed the relationship between tumor size, differentiation, TNM stage, lymph node metastasis and patient survival, these factors were all related to CHCHD2 expression." (PMID 32054470, 2020).
renal cell carcinoma (3 papers, 2020 to 2025). "CHCHD2 expression was significantly escalated in renal cell carcinoma (RCC) tissues, where it was notified that CHCHD2 expression was increased in stage II-IV of the disease." (PMID 33537311, 2020).
breast tumor (2 papers, 2021 to 2022). "In addition, it was shown that CHCHD2 dysregulates multiple genes that play a role in cell migration and cancer metastasis and that its expression is higher in cell lines derived from more aggressive breast tumors." (PMID 34900699, 2021).
Cognitive impairment (2 papers, 2021 to 2022). Abnormal cognition is characterized by deficits in thinking, reasoning, or remembering. "Increasing evidence has shown that CHCHD2 and CHCHD10 are associated with cognitive disorders and motor neuron diseases through their interactions with proteins such as OMA-1, OPA-1, TDP43, PINK, and p62." (PMID 36061599, 2022). "The review highlights the different roles played by CHCHD2 and/or CHCHD10 binding to various target proteins (such as OPA-1, OMA-1, PINK, and TDP43) and reveals their non-negligible effects in cognitive impairments and motor neuron diseases." (PMID 36061599, 2022).